SOX2 (SRY-box transcription factor 2)
Diseases named in the same sentence as SOX2 in open-access papers (continued):
Sharing a sentence is not in itself a finding about the gene and the disease.
ameloblastoma (16 papers, 2016 to 2026). The most common odontogenic tumor, arising from the epithelial component of the embryonic tooth and usually affecting the molar-ramus region of the mandible or maxilla. "BRAF(V600E)-mutated ameloblastoma cases showed significantly more SOX2-positive cells (24.5%) than in wild type (6.6%) (p < 0.05)." (PMID 35055392, 2022). "The identification of BRAF(V600E) mutation and the amplification of SOX2-positive cells in ameloblastomas imply the possible benefit of applying BRAF and SOX2 inhibitors in recurrent and un-resectable ameloblastomas." (PMID 35055392, 2022). "Several findings indicated that the SOX2 expressing cells played significant roles in propagation and recurrence of ameloblastoma and suggested BRAF(V600E) mutation may contribute to the expansion of SOX2-positive cell compartment." (PMID 35055392, 2022). "Conversely, ameloblastomas exhibit reduced SOX2 expression, predominantly restricted to peripheral ameloblast-like cells, accompanied by diminished staining intensity." (PMID 40699660, 2025). "The differential expression patterns of SOX2 and PITX2 underscore their potential diagnostic and prognostic value in distinguishing AC from ameloblastoma." (PMID 40699660, 2025). "Meta-analysis revealed a remarkable discriminative ability of SOX2 for ameloblastic carcinomas or odontogenic keratocysts over ameloblastomas." (PMID 37761874, 2023). "In our experiment, the cell viability was reduced in both ameloblastoma cell lines by silencing SOX2." (PMID 35055392, 2022). "Since the most accepted origin of ameloblastoma was the dental lamina cells, we also found that cells in epithelial rests of dental follicle showed SOX2 expression." (PMID 35055392, 2022). "In our investigation, we found the drug resistant clone of ameloblastoma cells revealed upregulation of SOX2." (PMID 35055392, 2022). "We also demonstrated that knockdown of SOX2 leads to decreased viability of ameloblastoma cells, and increased expression of SOX2 was associated with resistance to anti-BRAF small molecule inhibitors, vemurafenib and dabrafenib, in ameloblastoma cells." (PMID 35055392, 2022). "Few studies have revealed increased SOX2 expression in atypical ameloblastoma and ameloblastic carcinoma." (PMID 35055392, 2022). "In order to investigate the impact of SOX2 on the viability of ameloblastoma, we silenced SOX2 by shRNA through lentiviral system in ameloblastoma cell lines (AM1 and AM3)." (PMID 35055392, 2022). "The expression patterns of SOX2 in ameloblastoma to anti-SOX2 antibody crosses the histological subtypes." (PMID 35055392, 2022). "The SOX2 expression pattern of ameloblastomas was scattered with variable intensity as the expression pattern we observed in odontogenic epithelial rests." (PMID 35055392, 2022). "It is possible that these quiescent SOX2+ tumor cells give rise to the recurrent lesion in ameloblastoma." (PMID 35055392, 2022). "In comparison to human ameloblastomas, where SOX2 expression is low, CAA exhibits higher expression of SOX2." (PMID 34072517, 2021). "In oral lesions, SOX2 expression has been described in human odontogenic keratocysts and ameloblastoma." (PMID 34072517, 2021). "When diagnosing this tumour, sex-determining region Y-related high mobility group box 2 (SOX2) and high proliferation index (Ki-67) are necessary to distinguish it from ameloblastoma." (PMID 32388513, 2020). "We then assessed the expression of the dental epithelial stem cell markers BMI1 and SOX2 in human ameloblastoma biopsies." (PMID 32155948, 2020). "The Sox2 expression in these ameloblastomas has been related to their suggested origin in the Sox2-expressing dental lamina epithelium." (PMID 27611193, 2016). "In conclusion, this study provides evidence that Sox2 is significantly over-expressed in ameloblastoma and odontogenic keratocyst (OKC) compared to dentigerous cyst (DC), reflecting its association with lesions known for greater local aggressiveness and higher recurrence potential." (PMID 41176605, 2025).
ameloblastoma (continued). "This variable SOX2 expression pattern in ameloblastomas may suggest that additional molecular mechanism could be responsible for the neoplastic characteristics of this specific odontogenic tumor." (PMID 41176605, 2025). "Collectively, the role of SOX2-positive cells in ameloblastoma may be tumor-propagating and a driver of recurrence." (PMID 35055392, 2022). "To see if the labeling indices of SOX2 and Ki-67 can serve as a biomarker for the presence of mural extension of unicystic ameloblastoma, we interrogated these indices between mural type and intra-luminal/luminal type unicystic ameloblastoma." (PMID 35055392, 2022). "Knockdown of SOX2 prominently downregulated the cell viability of both ameloblastoma cell lines." (PMID 35055392, 2022). "Thus, providing a defined detection method for SOX2 in ameloblastoma, elucidating the identity as active or quiescence stem cells, and investigating the roles in drug response will be beneficial for developing personalized medicine in the future." (PMID 35055392, 2022). "Thus, we first examined the expression patterns of SOX2 using two different antibodies, which have been used in the literature, in 15 ameloblastoma cases." (PMID 35055392, 2022). "In this study, we first compared two different antibodies for precise detection of SOX2 in ameloblastomas, then explored the immunohistological staining patterns of SOX2 across the variants of ameloblastoma and verified their concordance to the sequencing results of BRAF." (PMID 35055392, 2022). "Thus, in this study, we aimed to study if SOX2-positive cells exist in ameloblastomas and their correlation with the clinicopathologic parameters." (PMID 35055392, 2022). "In this study, we sorted out the expression patterns of SOX2+ and Ki-67+ cells in dental follicle and ameloblastoma, confirmed a high rate of BRAF(V600E) mutation of ameloblastomas in Asian patients, and these mutated cases showed significantly more SOX2-positive cells." (PMID 35055392, 2022). "Exogenous activation of Wnt signalling using glycogen synthase kinase 3β inhibitors, lithium chloride (LiCl) and valproic acid (VPA), increased the cell size and decreased proliferation of cells and expression of Sox2 in 2 dimensionally cultured AM‐1 and human primary ameloblastoma cells." (PMID 34096124, 2021). "Key words:Odontogenic keratocyst; Ameloblastoma; Odontogenic tumor; SOX2; BCL-2." (PMID 31967981, 2020). "It was recently shown that ameloblastomas express high levels of the dental epithelial stem cell marker SOX2, suggesting that these tumors might originate from SOX2-expressing cells from the dental lamina." (PMID 32155948, 2020). "As their expression is associated with that of the dental epithelial stem cell markers BMI1 and SOX2, it is reasonable to hypothesize that Notch ligands and receptors might contribute to the maintenance of stemness of ameloblastoma cells." (PMID 32155948, 2020). "SOX2 is a key promoter of stem cell self-renewal, and its sustained expression might drive ameloblastoma pathogenesis." (PMID 32155948, 2020). "A number of studies have demonstrated expression of SOX2 in ameloblastoma." (PMID 31685919, 2019). "These SOX2+ dental lamina cells might play a significant role in the pathogenesis of ameloblastoma." (PMID 35055392, 2022). "Nuclear SOX2 expression was strong positive within OKC specimens in both basal and sub-basal layers, followed by Ameloblastoma which showed nuclear and cytoplasmic reaction, while most cases of DC recorded low positive scores." (PMID 41176605, 2025). "It needs further investigation to uncover what roles SOX2 and BRAF play in the tumor biology of ameloblastoma." (PMID 35055392, 2022). "Among heterogenous ameloblastoma cells, small‐sized and round‐shaped cells were found to be proliferative and expressed a marker of dental epithelial stem cells, SRY‐box 2 (Sox2)." (PMID 34096124, 2021).
ameloblastoma (continued). "In our study we observed a widespread expression of the dental epithelial stem cell markers SOX2 and BMI1 within ameloblastoma." (PMID 32155948, 2020). "The purpose of this experimental study was to compare the immunohistochemical expression of SOX2 and BCL-2 in Odontogenic Keratocyst (OKC) and Ameloblastoma (AB) specimens, and to identify a possible correlation in their expression." (PMID 31967981, 2020). "SOX2 and CD44 immunoexpression were significantly higher in conventional ameloblastoma." (PMID 42196620, 2026). "In contrast, weak or absent expression of SOX2 in ameloblastoma suggests different molecular pathways involved in its neoplastic behavior." (PMID 40078249, 2025). "Significant difference in SOX2 (IHC) staining scores was found between (OKC) and (DC) (P = < 0.001*), as well as between (Ab) and (DC) (P = 0.012*), (OKC) showed a significant higher SOX2 expression than ameloblastoma (P = 0.048*)." (PMID 41176605, 2025). "SOX2-positive cells were found in all cases regardless of BRAF status, with an average of 22.5% SOX2-positive cells in ameloblastomas." (PMID 35055392, 2022). "However, the role of SOX2 in clinical behavior of ameloblastoma and the cross-talks between SOX2 and MAPK pathway have not been clarified." (PMID 35055392, 2022).
prostate tumor (16 papers, 2012 to 2025). "SOX2 is associated with a higher Gleason score in a subset of prostate tumors that express SOX2." (PMID 28388544, 2017). "S5E), these data demonstrate that HIF1A promotes the expression of EZH2 and SOX2 under both hypoxic and normoxic conditions and enhances the progression of prostatic tumors." (PMID 35867798, 2022). "This suggests the relocation of SOX2 to novel oncogenic drivers during progression of prostate tumor." (PMID 35629138, 2022). "The expression of Sox2 in prostate tumors has been thought to promote a more aggressive tumor phenotype by promoting a “stem-cell like” tumor phenotype." (PMID 23326489, 2013). "Prostate tumors were either Sox2-positive or Sox2-negative, with the percentage of Sox2-positive tumors increasing with Gleason Score and metastases." (PMID 23326489, 2013). "The uniform expression of Sox2 in a subset of hormone naïve prostate tumors and the majority of castration-resistant metastases analyzed suggest multiple potential pathologic roles for Sox2 in prostate tumor initiation and progression." (PMID 23326489, 2013). "Here we show that Sox2 is expressed in the majority of normal prostate basal epithelial cells, and is uniformly expressed in a subset of prostate tumors." (PMID 23326489, 2013). "In the prostate, Sox2 expression has been observed in cells within the basal-epithelial cell layer of normal glandular epithelia, and in prostate tumors." (PMID 23326489, 2013). "Stable overexpression of SOX2 in the prostate tumor cell line DU145 has been reported to increase cell growth both in vitro and in vivo; whereas, inducible overexpression of SOX2 (3- to 5-fold) in DU145 cells inhibits tumor cell growth." (PMID 27145457, 2016). "Analyses of prostate tumors demonstrates that Sox2 is either uniformly expressed or uniformly absent." (PMID 23326489, 2013). "Due to the heterogenic character of PCa cell lines, and the lack of universal markers for CSC in prostate tumors, generated spheres from all human and murine PCa cell lines were stained for an array of CSC markers including: CD44, SOX2, CD117 (c-kit), and CD49f." (PMID 30211124, 2018).
brain cancer (15 papers, 2010 to 2025). A primary or metastatic malignant neoplasm affecting the brain. "HDAC2 activity regulates chromatin compaction that impacts the expression of SMAD3 and SOX2 and is, thus, critical for the self-renewal of brain cancer cells." (PMID 39063083, 2024). "We found that 89.2% of the quiescent mCherry+/mVenus+ cells co-expressed SOX2 and that 95.2% of mCherry+/mVenus+ cells were negative for proliferation marker Ki67 confirming the visualization of slow-cycling/quiescent cells in brain cancer organoids." (PMID 35970913, 2022). "The tumor initiation, maintenance and proliferation properties conferred by SOX2 may also introduce drug-resistance to CD133 (prominin-1) positive CSCs in GBM, making SOX2 a therapeutic target to treat the lethal brain cancer." (PMID 32092088, 2020). "Additionally, our studies suggest that the ALDHbright population validates the CSC phenotype based on the increased expression of brain cancer stem cells genes such as ALDH1A1, ITGA6, THY1, PROM1, and SOX2." (PMID 30646520, 2019).
malignant glioma (15 papers, 2007 to 2025). A grade III or grade IV glioma arising from the central nervous system. "In our study, we show for the first time that SOX2 knockdown led to an attenuated S-phase entry in malignant glioma cells which was caused by diminished levels of cyclinD1 and a concomitant decrease in the amount of phosphorylated RB protein." (PMID 22070920, 2011). "In another paper, it was reported that a CpG island in the Sox2 promoter that was hypomethylated in high Sox2-expressing malignant gliomas compared with normal tissues." (PMID 38473392, 2024). "They demonstrated that selective overexpression of SOX2 in the vast majority of malignant gliomas (on both mRNA and protein levels) in contrast to the normal cortex with nearly undetectable level of SOX2, provided an advantage for T cell-based immunotherapy." (PMID 30517668, 2020). "5-Aza is a DNA methyl-transferase inhibitor that has also been used successfully in epigenetic modification of SOX2 in adult malignant glioma cells." (PMID 25987129, 2015). "In the present study, we demonstrated the selective overexpression of SOX2 in the vast majority of malignant gliomas on the mRNA level as well as on the protein level." (PMID 17375044, 2007). "SOX2 was identified by screening an expression database for transcripts that are overexpressed in malignant glioma, but display minimal expression in normal tissues." (PMID 17375044, 2007). "Thus, we suggest the Sox2 staining was efficient for (i) separating malignant glioma cells from hematopoietic, interstitial cells, and oligodendrocytes, (ii) enriching for stem cells." (PMID 36348001, 2022). "In addition, the results indicate a critical role of SOX2 in adhesion and migration of malignant gliomas." (PMID 22070920, 2011). "We also wanted to investigate whether RNAi of SOX2 might be amendable to treat malignant gliomas." (PMID 22070920, 2011). "Given that SOX2 is predominantly expressed in embryonic and adult stems cells, including neural progenitor cells, and re-activates in cancers, including malignant gliomas, we hypothesized that the re-activation program of SOX2 may play an important role in the carcinogenesis and maintenance of GBM." (PMID 21211035, 2011). "On average, 15% (range 2–19%) of malignant glioma cells expressed IL-17R and more than 60% of IL-17R+ cells co-expressed the GSC markers CD133, Nestin, and Sox2." (PMID 26755664, 2016). "Therefore, SOX2 might represent a suitable target for RNAi to treat malignant gliomas." (PMID 22070920, 2011). "Although overexpression of Sox2 mRNA has been reported in malignant gliomas when compared with nonmalignant tissue, an exhaustive molecular and mechanistic analysis of Sox2 has never been performed." (PMID 22069467, 2011). "In the present study, we demonstrated that the transcription factor SOX2 is overexpressed in the vast majority of malignant gliomas, whereas expression in normal brain and other non-malignant tissues is almost negligible." (PMID 17375044, 2007). "Compared to cDNA from pooled normal brain, SOX2 was overexpressed in almost all (9 out of 10) malignant glioma samples, whereas expression in other, non-malignant tissues was almost negligible." (PMID 17375044, 2007). "However, Sox2 expression can also be demonstrated in whole GBM specimens, and though Sox2 has been described as a TSC marker, it is more likely an indicator of the aberrant differentiation that is characteristic of malignant gliomas." (PMID 24212632, 2011).